RN7SL725P (RNA, 7SL, cytoplasmic 725, pseudogene)
Gene: Miscellaneous RNA gene on chromosome Y (25,458,926 to 25,459,184, forward strand). Ensembl gene ENSG00000278242.
Homologues: Orthologues: chimpanzee Metazoa_SRP (54% identical). Paralogues in human: RN7SL818P (100% identical), RN7SL536P (77% identical), Metazoa_SRP (77% identical), RN7SL106P (77% identical), RN7SL238P (77% identical), RN7SL545P (77% identical), RN7SL759P (77% identical), RN7SL417P (75% identical), RN7SL209P (71% identical), RN7SL736P (69% identical), RN7SL214P (68% identical), RN7SL176P (67% identical), and 705 more.